MIR575 (microRNA 575)
Synonyms: hsa-mir-575; MIRN575
Gene: MicroRNA gene on chromosome 4 (82,753,337 to 82,753,430, reverse strand). Ensembl gene ENSG00000207746.
Gene Ontology:
Biological process: miRNA-mediated post-transcriptional gene silencing
Cellular component: RISC complex
Homologues: Orthologues: chimpanzee ptr-mir-575 (99% identical).